MIR671 (microRNA 671)
Synonyms: hsa-mir-671; MIRN671; mir-671
Gene: MicroRNA gene on chromosome 7 (151,238,421 to 151,238,538, forward strand). Ensembl gene ENSG00000284191.
Gene Ontology:
Biological process: miRNA-mediated post-transcriptional gene silencing
Cellular component: RISC complex
Homologues: Orthologues: chimpanzee ptr-mir-671 (100% identical), macaque mml-mir-671 (100% identical), pig MIR671 (90% identical), guinea pig MIR671 (83% identical), mouse Mir671 (82% identical), rabbit MIR671 (70% identical).